NCAM1 (neural cell adhesion molecule 1)
Diseases named in the same sentence as NCAM1 in open-access papers (continued):
Sharing a sentence is not in itself a finding about the gene and the disease.
tumor (1,352 papers, 1990 to 2026). "NCAM1 expression is positively associated with cancer-associated neurogenesis and negatively with tumour invasiveness." (PMID 38308202, 2024). "For various cancer types, elevated expression of Ncam1/NCAM1, like we observed after ephrinA5-Fc stimulation, is associated with reduced tumor cell migration and better prognosis." (PMID 37880732, 2023). "The univariate analysis revealed that the level of NCAM1 (P = 0.008), age (P = 0.001), grade (P = 3.69E-08), stage (P = 8.63E−12) and M (metastasis) (P = 7.93E−17) and T (tumor) (P = 1.47E−10) were associated with poor OS." (PMID 38087309, 2023). "Our data also showed that the NCAM1 gene level is linearly correlated with mutation burden, i.e. the number of mutations found in the expressed genes in tumor." (PMID 34857809, 2021). "In vitro and in vivo experiments indicated that NCAM1 is necessary for EMT induction and maintenance and furthermore, high NCAM1 expression level was found to be associated with tumor invasion." (PMID 31083655, 2019). "The level of COL1A1 expression was higher in the muscular and serosa invaded tumors, while NCAM1 expression tended to be negatively associated with tumor invasion." (PMID 25860484, 2015). "NCAM1 RNA level is also positively associated with the mutation burden in tumor (P = 0.023)." (PMID 34857809, 2021). "We performed immunostaining of p-WT Xn and parental WT for the following: WT1, a specific clinical diagnostic marker for WT; NCAM1, a putative marker for a tumour progenitor population previously shown in in vitro assays of primary cell cultures of WT; and Ki-67, a cell proliferation marker." (PMID 23239665, 2013). "Previous studies have identified SIX2+CITED1+, PROM1+ or NCAM1+ALDH1+ tumor cells as potential CSC-like populations in WT." (PMID 40098972, 2025). "In this study, relapse-associated Scissor+ tumor cells were consistent with previous studies, showing significant upregulation of CSC markers SIX2, PROM1, and NCAM1." (PMID 40098972, 2025). "Our immunoinfiltration analysis revealed a significant positive correlation between NCAM1 and γδ T cells, suggesting its potential role in modulating anti-tumor immunity." (PMID 40908816, 2025). "Four primary cell populations were first identified using canonical cell markers: WT tumor cells (WT1, NCAM1, SIX1, SIX2, PAX2), cancer-associated fibroblasts (CAFs) (ACTA2, TAGLN, COL1A1, PDGFRB), endothelial cells (PECAM1, CLDN5, ENG, VWF) and immune cells." (PMID 40098972, 2025). "We further validated the expression of Chromogranin A, Synaptophysin, PAX6 and NCAM1 using immunohistochemistry staining on MAP model tumor sections." (PMID 38609433, 2024). "These cells can interact directly with tumor cells via neural cell adhesion molecule 1, facilitating tumor cell invasion into nerves." (PMID 39492832, 2024). "NCAM1 activation induces a conformational change in SCs by making membrane protrusions appear that facilitate their dispersion among tumor cells, promoting NI." (PMID 38542008, 2024). "In agreement with the inverse correlation of NCAM1 expression with tumor cell migration, we found reduced motility of CB cells, when analyzing their migration in vitro 24 h after ephrinA5-Fc stimulation." (PMID 37880732, 2023). "Among the top ten MRs identified by MARINa, only two genes (EGFR and NCAM1) have abnormal copy number for at least 30% of tumor samples." (PMID 37894336, 2023). "NCAM1 forms a complex with N-cadherin and FGFRs to promote cell adhesion, affecting tumor progression in various ways." (PMID 35053442, 2022). "NCAM1 is present in high levels in RB tissue and cell lines, confirming the neuroectodermal origins of this tumor; furthermore, it has been demonstrated to be involved in the immunomodulation of RB." (PMID 36362243, 2022). "Examples of receptors overexpressed in SCLCs included ERBB3 (tumor ligands NRG1, NRG2) and GDNF receptor 1 encoding GFRA1 (ligand NCAM1)." (PMID 36271074, 2022).
tumor (continued). "The expression of Chga, Th, Dbh, Syp, Ncam1 and Alkal2 was also observed in the tumour transcriptome of all three genotypes (Table EV4), which is in agreement with our histological analysis." (PMID 33411331, 2021). "We then performed the immunohistochemical (IHC) staining of DLL1, a representative protein in the Notch signaling pathway, and NCAM1, a representative protein of infiltrating natural killer cells, in the tumor tissues of 8 patients." (PMID 34857809, 2021). "NK cell populations were defined as NKp46+ and CD3– due to high expression of CD56 (NCAM‐1) on GBM tumour cells within the sample." (PMID 31784984, 2020). "In order to validate our results, we next preformed qRT-PCR analysis that revealed high NCAM1 expression in primary PPB tumor compared to healthy adult lung control samples (top) and in late passages PPB-Xn in comparison to primary PPB (bottom)." (PMID 31477684, 2019). "Our data revealed increased expression of both NCAM1 and FGFs in tumor samples in comparison to normal adult lung and along PDX propagation." (PMID 31477684, 2019). "We observed a significant difference in tumor growth rate in anti-NCAM1 antibody treated mice vs. the control group following treatment." (PMID 31477684, 2019). "Upregulation of neural cell adhesion molecule 1 has been reported to promote the formation of focal adhesions in mesothelium‐derived tumours 47, but a possible functional role in MMT is yet to be elucidated." (PMID 29774544, 2018). "In contrast, the tumor-specific cluster C3 appears less differentiated with features typical of CD56brightCD16neg NK cells (NCAM1, CD2, CD27, SELL, CD69) as well as a signature of tissue residency (CD69 and ITGA1) and of TGF-β-induced genes (SMAD7, TGFB1, PMEP1, SKIL)." (PMID 41145419, 2025). "In addition, cytokine-secreting CD56 (NCAM1) NK cells were found to be enriched in tumour lesions of imatinib-treated patients and independently predicted progression-free survival (PFS)." (PMID 39070147, 2024). "Among the plasma membrane proteins, NCAM1 directly contacts tumor cells with SCs." (PMID 38542008, 2024). "In a cohort of individuals with non-small cell lung cancer and a cohort with small cell lung cancer, low tumor menin expression was correlated with high expression of NCAM1, high expression of neuron-specific enolase, and shorter median survival time compared to high tumor menin expression." (PMID 39336822, 2024). "Notably, these markers have previously been linked to different cell types, including endothelial cells (CD44, ENG, F3, MCAM, and ITGB1), immune cells (CD14, CD44, CSPG4, ENG, HLA-DR/DP/DQ), and neuronal cells (NCAM1), as well as astrocytes and tumor cells." (PMID 39594703, 2024). "In addition to its function in neurons, NCAM1 is a well-known tumor suppressor in numerous cancer types." (PMID 37880732, 2023). "The cytoplasm of tumor cells was positive for neural cell adhesion molecule 1 (NCAM1)." (PMID 34928410, 2021). "It would be interesting to see if NCAM1 plays a similar role in gastric and other neoplasms." (PMID 28846697, 2017). "Tumor cells of neural origin often express the neural cell adhesion molecule 1 (NCAM1)." (PMID 25148252, 2014). "Reduced copy number and expression of NCAM1 in tumours bearing KRAS mutations, as seen in our data, has not previously been reported." (PMID 21385341, 2011). "Relative to the other AD samples, both AD5 and the AYA group exhibited higher expression of genes associated with aggressive tumor features and inflammation (e.g., CXCL2, TUBB3, RRM2, and MMP1) and lower expression of differentiation markers and metastatic regulators (e.g., KIT and NCAM1)." (PMID 41374320, 2025). "One subpopulation expressed CD44 + CXCR3 + CXCR4 + PRF1 + and GZM family genes, while the other expressed XCL1 + NCAM1 + GNLY + and KIR family genes, suggesting that these T cells possess a robust capacity to mediate tumor cell apoptosis." (PMID 40411616, 2025).
tumor (continued). "Nevertheless, NCAM1, NRCAM, SLIT2, ALCAM, NRP1, and NRP2 also showed mild expression in Stage 4 tumor cells (primarily in cluster cIV)." (PMID 40448172, 2025). "SCs express neural cell adhesion molecule 1 (NCAM1), which separates tumor cell clusters into individual cells to induce their migration towards SCs and spread along nerves." (PMID 38334648, 2024). "Tumor-wide (100%) positivity was exhibited only for four event-case pairs (PTPRZ1-03 in tumor T2; NCAM1-01 in T24; DLL3-02 in tumors T15 and T16)." (PMID 38493204, 2024). "In CIN3 versus normal biopsies, the tumour markers CDKN2A and KRT7 had the highest fold-change, while genes related to a favourable immune response, ARG1 and NCAM1, had the lowest." (PMID 39712018, 2024). "Consistently, immunohistochemistry in PARCB tumor sections showed increased mitochondrial content (TOMM20) and neuroendocrine (NCAM1) protein expression in PGC-1α-High tumors." (PMID 39589879, 2024). "In SHH, Group 3 and Group 4 MBs, we identified upregulated NCAM-1 and MDK signaling as facilitators for communication between different tumor clusters." (PMID 39659836, 2024). "Tumor biopsies obtained during surgery were analyzed for expression of NCF2, CYBB, CD68, CD163, and NCAM1 by RT-PCR." (PMID 38598844, 2024). "NCAM1’s roles in neurogenesis and angiogenesis are particularly relevant in GBM, where the tumour microenvironment requires vascular support and neural integration to sustain its growth and invasiveness." (PMID 39457550, 2024). "In the tumor tissues of NEPC patients, AR signaling is low or lost, and such typical NE markers as neuronal-specific enolase 2 (ENO2), synaptophysin (SYP), NCAM1 and chromogranin A(CHGA) are remarkably elevated." (PMID 37563661, 2023). "Although the expression of CHGA, NCAM1, and SYP varied among these three individuals, all of them showed a co-expression of AR and NE markers in the same areas of tumor sites." (PMID 36033483, 2022). "In detail, the expression levels of NCAM1 and IGF2 were significantly higher in tumor tissue compared to adjacent normal tissue from the same patient (P-value of < 0.01 and < 0.05, respectively)." (PMID 36284226, 2022). "For the remaining seven S100P- iCCAs (P09, P10, P12, P13, P14, P15, and P19), they expressed iCCApps markers NCAM1 and CDH2, which were mutually exclusive with the expression of S100P, confirming the different origins of these tumor cells." (PMID 35347134, 2022). "The main cell clusters included T cells (CD3E and CD3D), B cells (CD19), natural killer cells (NCAM1, FCGR3A and KLRD1), myeloid cells (CD86 and CD163) and tumor cells (EPCAM, KRT8 and KRT18)." (PMID 36497182, 2022). "Subclustering of natural killer (NK) cells revealed well-known NCAM1- and FCGR3A- expressing subsets and an interesting keratin (KRT81 and KRT86)-expressing subset potentially enriched in tumor tissues." (PMID 36423636, 2022). "The targeted genes, ENOX1, NCAM1, SAMD4A, and ZC3H10, are closely related to CRC tumour-infiltrating macrophages." (PMID 35155186, 2021). "Histological and immunoblot analysis revealed small round blue cell tumours poor in stroma that expressed NCAM1, synaptophysin (SYP), Chromogranin A (CGA) and MYCN in Rosa26_Alkal2;Th‐MYCN tumours, in agreement with NB." (PMID 33411331, 2021). "Xenograft tumor of HCT 116 showed an increased expression of neuronal genes MAP2 and SYN1, neural stemness genes CDH2, MSI1, NCAM1, SOX2/9, VIM and ZEB2, and genes for mesodermal and endodermal tissues (ACP5, AFP, DESMIN, HNF4A and KRT8)." (PMID 33468253, 2021). "Significant correlation was observed between the polarised M2 macrophages and ENOX1, NCAM1, SAMD4A, and ZC3H10 with respect to tumour purity." (PMID 35155186, 2021). "We used this model to dissect tumor biology and uncovered a novel therapeutic target for PPB, namely Neural cell adhesion molecule 1 (NCAM1)." (PMID 31477684, 2019).
tumor (continued). "Immediately after surgery, tumor samples were frozen in liquid nitrogen and stored in a biofreezer at –80°C for assessment of E-cadherin 1 (CDH1), SLUG (SNAI2), and NCAM (NCAM1) by real-time PCR." (PMID 29267504, 2017). "Besides lineage-specific transcription factors, tumor cell clusters shared expression of epithelial marker gene EPCAM and neuron marker gene NCAM1." (PMID 38658971, 2024). "However, since we observed activation of tumor-derived NCAM-1 signaling in Group 3 tumors, which are known for being “immunologically cold,”48 we suggest that NCAM-1 signaling occurs within different cellular compartments depending on MB subgroup." (PMID 39659836, 2024). "Additionally, in the tumor specimens of advanced PCa patients, we observed low TOMM20 but high NCAM1 expression in the AR negatve PCa cells." (PMID 37563661, 2023). "Pro-tumorigenic tumors displayed upregulation of genes related to pro-tumoral processes such as adhesion or migration (NCAM1), proliferation (CDK1, TOP2A) or extensively described tumor markers (CDKN2A, MTOR), among others, while showing an impairment in immune-related functions." (PMID 35329826, 2022). "However, the positive cells of NCAM1 (2.36%) and CDH2 (31.86%) accounted for a very low proportion of the total tumor cells in these seven S100P- iCCAs." (PMID 35347134, 2022). "In tumor nerves with PNI there is an increase in Schwann cells (GFAP+, Glial fibrillary acidic protein) and they intercalate with cancer cells by direct contact through NCAM1 (neural cell adhesion molecule 1)." (PMID 32555170, 2020). "Also, we identified NCAM1, CNTN1, SCG2, CADM1, IL-8, NPTX1, and APOD as PSCB in the tumor secretome." (PMID 31455042, 2019). "Next, we performed a qRT-PCR analysis on treated and untreated tumor cells revealing significant downregulating of NCAM1 expression, as well as downregulation of several self-renewal genes (e.g., LIN28A, OCT4, and KLF4) in the anti-NCAM1 treated cells." (PMID 31477684, 2019). "As expected, NB5t primary cells showed increased expression of mesenchymal genes (NT5E, ENG, ACTA2, MME, CD44, VIM or ALPL), while NB5t tumor sample expressed mostly neuronal genes (TH, ENO2, NCAM1, DDC or CHGB) reflecting the neuroblastic phenotype of stage 4/M NB tumors." (PMID 29163787, 2017). "Neural lineage markers, such as NCAM1 (early) and NPTX1 (neuronal), were highly expressed in 143BNSC tumours, whereas genes involved in cancer proliferation, including EYA2, VCAN, HMGA1 and TXNIP, were highly expressed in 143BGBM tumours." (PMID 27551510, 2016). "In tumorigenesis, NCAM1+CD133−marks SIX2+ blastema that includes the ALDH1+ WTcancer stem/initiating cells, while NCAM1+CD133+ andNCAM1−CD133+ specifying early and lateepithelial differentiation, are severely restricted in tumor initiation capacity andtumor self-renewal." (PMID 27020553, 2016). "A number of genes demonstrated reduced copy number and expression in KRAS mutant tumours, including putative tumour suppressor genes (FOXO3, EXTL2, PPP2R1B), negative regulators of the receptor tyrosine kinase oncogenic pathways (PTPRK, DGKZ, NCAM1), and negative regulators of Ras (EPHB2)." (PMID 21385341, 2011). "Specifically, NCAM1 may leverage its adhesion properties to facilitate γδ T cell recruitment within the TME, thereby reshaping the local immune landscape and enhancing immune surveillance against tumor cells." (PMID 40908816, 2025). "This revealed that tumor cells in MBMs not only exhibited significantly upregulated tumorigenesis and maintenance genes (e.g., MET and TBX2), but also expressed neural differentiation markers (e.g., NRG3, NELL1, NCAM1, ADNP) and cell adhesion molecules (e.g., CDH1, PRKCA)." (PMID 41284647, 2025). "To ensure our sorting purity, we compared tumor-infiltrating NK and T cell gene expression, highlighting unequivocal differences in DGE of canonical NK and T cell genes among the respective subsets, specifically NCAM1 and IL2Rb in NK cells, and CD3, CD8 and CD28 in T cells." (PMID 35874727, 2022).
tumor (continued). "Thus, the up-regulation of COL1A1 and down-regulation of NCAM1 expression could not only distinguish between cancer and normal tissues, but also divide the cancer patients into different tumor stages." (PMID 25860484, 2015). "SMARCA4 expression was positively correlated with multiple NE genes including SYP, CHGA, INSM1, DLL3 and NCAM1 and negatively correlated with non-NE factors REST, NOTCH2, and YAP1 in both SCLC cell lines and patient tumor databases." (PMID 39080761, 2024). "Using multiplex IHC assays, we showed that FGFBP2+NKT cells (positive for CD8, NCAM1, and FGFBP2, but not for CD4) were mainly present in the para-tumor regions and were sparsely distributed in the tumor regions." (PMID 38065972, 2023). "We found that sorted tumor-infiltrating CD33high cells expressed high levels of CD33 gene, while lacked gene expression of CD3E, CD8A and NCAM1 (gene for CD56), compared to CD8+ T cells." (PMID 33000418, 2021).